EMILIN1 (elastin microfibril interfacer 1)
Description:
Involved in elastic and collagen fibers formation. It is required for EFEMP2 deposition into the extracellular matrix, and collagen network assembly and cross-linking via protein-lysine 6-oxidase/LOX activity. May be responsible for anchoring smooth muscle cells to elastic fibers, and may be involved in the processes that regulate vessel assembly. Has cell adhesive capacity.
Synonyms: EMI; DKFZp586M121; gp115; EMILIN; ATBFS; HMN10; HMND10
Tractability: Small molecule: it has a binding pocket of medium quality. Antibody: UniProt places it where antibodies can reach, with high confidence; its Gene Ontology location is reachable by antibodies, with high confidence; UniProt predicts a signal peptide or a membrane-spanning region.
Gene: Protein-coding gene on chromosome 2 (27,078,044 to 27,086,408, forward strand). Ensembl gene ENSG00000138080.
Subcellular location: Secreted, extracellular space, extracellular matrix
Pathways (Reactome):
Extracellular matrix organization: Molecules associated with elastic fibres
Gene Ontology:
Molecular function: identical protein binding; integrin binding involved in cell-matrix adhesion; molecular adaptor activity; protein binding; extracellular matrix constituent conferring elasticity; extracellular matrix structural constituent
Biological process: cell migration; cell-matrix adhesion; positive regulation of defense response to bacterium; aortic valve morphogenesis; cell adhesion; elastic fiber assembly; negative regulation of angiogenesis; negative regulation of cell activation; negative regulation of collagen biosynthetic process; negative regulation of collagen fibril organization; negative regulation of ERK1 and ERK2 cascade; negative regulation of gene expression; negative regulation of macrophage migration; negative regulation of SMAD protein signal transduction; negative regulation of transforming growth factor beta receptor signaling pathway; negative regulation of vascular endothelial growth factor receptor signaling pathway; negative regulation of vascular endothelial growth factor signaling pathway; positive regulation of blood coagulation; positive regulation of extracellular matrix assembly; positive regulation of gene expression; cell adhesion mediated by integrin; positive regulation of angiogenesis; regulation of blood pressure; regulation of cell population proliferation
Cellular component: EMILIN complex; extracellular exosome; extracellular matrix; extracellular region; integrin alpha4-beta1 complex; elastic fiber; microfibril
Genetic constraint (gnomAD): Loss-of-function variants: 46 observed, 70.67 expected, observed/expected ratio (o/e) 0.65, 90% interval 0.51 to 0.83. The upper end of that interval is the gene's LOEUF score, 0.83, which puts it in group 3 of 6, group 1 being the genes least tolerant of losing a copy. Missense variants: 1,312 observed, 1,298.6 expected, observed/expected ratio (o/e) 1.01, 90% interval 0.96 to 1.06. Synonymous variants: 604 observed, 560.87 expected, observed/expected ratio (o/e) 1.08, 90% interval 1.01 to 1.15.
Gene-disease validity (ClinGen):
ClinGen rates the evidence that EMILIN1 causes each of these diseases.
arterial tortuosity-bone fragility syndrome (autosomal recessive): Definitive. A syndromic disease with a spectrum of manifestations in the cardiovascular system and other organ systems caused by disease-causing variants in the EMILIN1 gene, inherited in an autosomal recessive manner.
Homologues: Orthologues: chimpanzee EMILIN1 (99% identical), macaque EMILIN1 (98% identical), dog EMILIN1 (92% identical), pig EMILIN1 (92% identical), rat Emilin1 (88% identical), mouse Emilin1 (87% identical), guinea pig EMILIN1 (87% identical), rabbit EMILIN1 (85% identical), tropical clawed frog emilin1 (41% identical), zebrafish emilin1b (38% identical), zebrafish emilin1a (34% identical). Paralogues in human: EMILIN2 (24% identical), EMILIN3 (17% identical), MMRN1 (14% identical), MMRN2 (14% identical).
Diseases named in the same sentence as EMILIN1 in open-access papers:
EMILIN1 is named in the same sentence as 84 diseases in open-access papers, as found by Europe PMC text mining. Sharing a sentence is not in itself a finding about the gene and the disease. The quoted sentences say what the papers report.
breast cancer (11 papers, 2016 to 2025). A primary or metastatic malignant neoplasm involving the breast. "EMILIN1 is an extracellular matrix protein, and its up-regulation has been associated with a better prognosis of patients with breast cancer." (PMID 40429863, 2025). "High EMILIN1 expression was also associated with better prognosis of patients with breast cancer, underscoring its functional significance for the recruitment of cytotoxic T cells into the tumor area." (PMID 38505604, 2024). "EMILIN1 is highly expressed in CAF, and the high EMILIN-1 expression at the tumor margins is associated with increased CD8+ T-cell infiltration in breast cancer." (PMID 39892781, 2025). "The protective role of EMILIN-1 was further validated in a HER2-driven breast cancer model by crossing Emilin1−/− mice with MMTV-Δ16HER2 transgenic mice that spontaneously develop multifocal mammary adenocarcinomas." (PMID 40643467, 2025). "LC–ESI–MS/MS analysis, combining high-performance liquid chromatography resolution with mass spectrometer accuracy, detected elevated levels of EMILIN-1 peptides among other plasma proteins in breast cancer patients." (PMID 40643467, 2025). "Immunofluorescence and immunohistochemical analyses confirmed the positive correlation between EMILIN1 expression in CAF and CD8+ T cell infiltration, and breast cancer patients with high EMILIN1 expression showed significantly improved survival rates." (PMID 40867511, 2025). "Nonetheless, our study of human breast cancer samples revealed a significant decrease in EMILIN1 expression in metastatic lesions, most of which were collected from lymph nodal locations." (PMID 38184660, 2024). "Histological analysis of 75 breast cancer samples confirmed that high EMILIN1 expression in the tumor margins was related to high CD8+ T-cell infiltration, consistent with our spatial gene expression analysis." (PMID 38505604, 2024). "In summary, our data support that EMILIN1 plays a role in controlling mammary gland development and initiating breast cancer in a murine model of HER2+ BC." (PMID 38184660, 2024). "The potential role of EMILIN-1 in breast cancer radioresistance may stem from its complex interactions with ECM components and immune-modulatory functions within the TME, highlighting the complexity of its roles." (PMID 40643467, 2025). "Moreover, breast cancer cases defined as EMILIN1-high had a significantly lower proportion of Ki-67-positive cancer cells." (PMID 38505604, 2024). "Notably, we observed that EMILIN1 expression was progressively lost as we transitioned from healthy mammary tissue to primary breast cancer." (PMID 38184660, 2024). "EMILIN-1 is considered a tumor-suppressor-like protein in skin, cancer, and breast cancer." (PMID 34299025, 2021). "Elevated EMILIN1 expression at the tumor periphery is associated with robust CD8 T-cell infiltration, and such increased EMILIN1 expression correlates with an improved prognosis in breast cancer patients, underscoring its functional relevance in the recruitment of cytotoxic T cells to the TME." (PMID 39439806, 2024). "EMILIN-1, an ECM glycoprotein, has shown tumor-suppressive effects in colon cancer, melanoma, and breast cancer." (PMID 39892781, 2025).
gastric cancer (10 papers, 2018 to 2025). A primary or metastatic malignant neoplasm involving the stomach. "Transgenic studies demonstrate that EMILIN-1 deficiency leads to excessive tumor-associated lymphangiogenesis, accelerated gastric cancer cell dissemination via LVs, and more aggressive lesion development." (PMID 40643467, 2025). "Recently, EMILIN-1 was suggested to increase TSPAN9 expression in gastric cancer cell lines and form a complex with TSPAN9 to synergistically inhibit FAK/Ras/Erk pathway and suppress invasion and migration." (PMID 35739492, 2022). "TSPAN9 expression and the invasion and metastasis of gastric cancer cells were observed by the functional assays following EMILIN1 over-expression." (PMID 31242895, 2019). "To clarify the molecular mechanism of EMILIN1 and TSPAN9, we overexpressed TSPAN9 and EMILIN1 + TSPAN9 in gastric cancer cells, respectively." (PMID 31242895, 2019). "EMILIN1 synergistically regulates gastric cancer cell invasion and metastasis by promoting TSPAN9 expression." (PMID 31242895, 2019). "It was further found that the simultaneous high expression of TSPAN9 and EMILIN1 was more inhibitory of gastric cancer cell migration and invasion than was the overexpression of TSPAN9 alone." (PMID 31242895, 2019). "We have demonstrated that EMILIN1 induces anti-tumor effects by up-regulating TSPAN9 expression in gastric cancer." (PMID 31242895, 2019). "We found that TSPAN9 can disrupt gastric cancer cell invasion and migration, and EMILIN1 can synergistically promote the anti-cancer effects of TSPAN9." (PMID 31242895, 2019). "In gastric cancer, conflicting reports exist regarding the EMILIN-1 role." (PMID 40643467, 2025). "Additionally, Elastic Microfibril Interface Located Protein 1 (EMILIN1) can synergistically inhibit gastric cancer cell invasion and metastasis through enhancing TSPAN9 expression." (PMID 41347075, 2025). "The contribution of the tumor microenvironment and extracellular matrix to the aggressive biology of Gastric Cancer (GC) has been recently characterized; however, the role of EMILIN-1 in this context is unknown." (PMID 38941035, 2024). "In particular, Multimerin-2 and EMILIN-2 affect angiogenesis and vascular efficiency, whereas EMILIN-1 affects lymphangiogenesis, which may also play a role in gastric cancer development representing an important route for metastatic dissemination." (PMID 30544909, 2018). "Furthermore, the extracellular matrix glycoprotein elastin microfibril interfacer 1 (EMILIN1) may exert a synergistic effect with Tspan9 on the migration and invasion of gastric cancer cells." (PMID 38389703, 2024). "Therefore, we tested whether the addition of TSPAN9 to the CO1A1, COL5A1, ITGA4, and EMILIN1 Cox model can decrease the poor prognostic impact of CAF infiltration in gastric cancer." (PMID 35739492, 2022). "Hence, membrane proteins TSPAN9 and EMILIN1 may represent novel therapeutic targets for the treatment of gastric cancer." (PMID 31242895, 2019). "For example, EMILIN1 suppresses tumor growth, and deregulation of EMILIN2 in gastric cancer promotes tumor growth and angiogenesis." (PMID 38971308, 2024). "We then performed immunofluorescence measurements of EMILIN1 and TSPAN9 in cells and found that they co-localized in gastric cancer cell." (PMID 31242895, 2019). "In conclusion, in this study we characterized the expression of EMILIN-1, Multimerin-2 and EMILIN-2 in the gastric normal mucosa and in gastric cancer." (PMID 30544909, 2018). "Elucidation of these molecular and cellular mechanisms may present EMILIN-1 and TSPAN9 as new therapeutic targets in gastric cancer." (PMID 35739492, 2022). "One limitation to the study may be that only the TIDE algorithm predicted a poor prognostic impact for CAF infiltration in COL1A1, COL5A1, ITGA4, EMILIN1, and TSPAN9 multivariate Cox model in gastric cancer." (PMID 35739492, 2022). "A similar mechanism may explain the context-dependent role of EMILIN-1 and TSPAN9 in gastric cancer." (PMID 35739492, 2022).
gastric cancer (continued). "A recent study reported that the action of EMILIN-1 to inhibit the MAPK pathway and suppress proliferation in gastric cancer cells might depend on Tetraspanin9 (TSPAN9), which is a member of the tetraspanin family membrane receptors with four transmembrane domains." (PMID 35739492, 2022). "Since overexpression of only EMILIN1 did not induce a similar anti-tumor response in gastric cancer cell lines, it was suggested that the anti-tumor effect of EMILIN-1 may be dependent on TSPAN9." (PMID 35739492, 2022). "Therefore, whether EMILIN1 and TSPAN9 exert an anti-tumor effect or pro-tumorigenic effect in gastric cancer is not clear yet." (PMID 35739492, 2022).
colon carcinoma (5 papers, 2020 to 2025). "Degradation and consequent loss of EMILIN-1/gC1q in the tumor environment promotes tumor initiation and progression in colon cancer." (PMID 39892781, 2025). "Knocking out EMILIN1 or transgenic expression of an EMILIN1 mutant with impaired binding to integrin α4β1 increased the susceptibility of mice to develop colon cancer." (PMID 35739492, 2022). "It is well established that main member of this family, EMILIN1, interacts with the β1-containing integrins and the gC1q domain, and abrogation of EMILIN1-β1 integrin interactions promotes colon carcinoma progression." (PMID 33543032, 2020). "EMILIN-1 is an essential structural element for the maintenance of lymphatic vessel (LV) integrity and displays anti-proliferative properties as demonstrated in skin and colon cancer." (PMID 38941035, 2024). "Importantly, analysis in EMILIN-1 KO showed that its ablation in the microenvironment promoted tumor progression in skin, melanoma, and colon cancer models." (PMID 34299025, 2021). "EMILIN-1 suppresses the RAS-ERK signaling pathway through α4β1 integrin, leading to decreased cell proliferation and tumor cell growth in colon cancer." (PMID 39892781, 2025). "Indeed, in other tumor models, we found that the absence of EMILIN-1 accelerates tumor development and increases the number and size of colon tumors, while its expression halts cell proliferation and counteracts lymphatic dysfunction in the AOM/DSS model of inflammatory colon carcinogenesis." (PMID 38941035, 2024).
Hypertension (5 papers, 2009 to 2024). The presence of chronic increased pressure in the systemic arterial system. "The levels of the elastin microfibril interfacer 1 (EMILIN1) gene that encodes an extracellular matrix glycoprotein were found to be altered in people with hypertension and obesity." (PMID 37606455, 2023). "The role of EMILIN1 is extensively studied in EMILIN1-deficient mice, which display aortic valve malformations and hypertension." (PMID 32486169, 2020). "Hypertension is found in Emilin1 deficient mice and numerous studies indicate that hypertension is a risk factor for thrombosis." (PMID 21569335, 2011). "Our findings don't support positive association of Emilin1 gene with EH, but the interaction of age and genotype variation of rs3754734 and rs2011616 might increase the risk to hypertension." (PMID 19922630, 2009). "The EMI domain is linked to hypertension and TGF-β processing, while adhesive functions of EMILIN1 are related to its gC1q domain." (PMID 32486169, 2020). "Because the EMI domain of Emilin 1 was shown to inhibit TGFβ maturation in the context of hypertension, we assessed whether EMID2 could do the same." (PMID 38195652, 2024). "Recently relevant advances urge further researches to investigate the role of Emilin1 gene in regulating TGF-β signals involved in elastogenesis and vascular cell defects of essential hypertension (EH)." (PMID 19922630, 2009).
aortic valve disease (4 papers, 2014 to 2023). "Inhibition of the MAPK-ERK pathway in vivo has been shown to attenuate aortic valve disease progression in Emilin1-deficient mice." (PMID 37908840, 2023).
gastric tumors (4 papers, 2018 to 2025). "The hazard ratio of CAF infiltration in COL1A1, COL5A1, ITGA4, EMILIN1, and TSPAN9 signature was even higher, presenting a 36.8 times higher risk of death in gastric tumors with high CAF infiltration." (PMID 35739492, 2022). "Interestingly, when EMILIN-2 expression was strongly decreased in gastric tumor samples, the organization of the EMILIN-1 fibers was also altered." (PMID 30544909, 2018). "Given that both blood and lymphatic vessels represent a route for metastatic cell dissemination, the altered expression of EMILIN-2 and EMILIN-1 may significantly impact of the progression of gastric tumors." (PMID 30544909, 2018). "In this study, we confirm in the gastric tumor microenvironment that the reduced levels of EMILIN-1 or its functional impairment could promote the conspicuous presence of inflammatory cells, probably as a consequence of reduced clearance by the dysfunctional LVs." (PMID 38941035, 2024).
aortic aneurysm (3 papers, 2017 to 2025). A ruptured aneurysm located in the wall of the proximal portion of the descending aorta proceeding from the arch of the aorta. "EMILIN1 gene mutations are usually associated with overt connective tissue disease, such as increased skin elasticity, joint hypermobility, and aortic aneurysm." (PMID 40909027, 2025). "We found that the increasing diameter of aortic aneurysm significantly correlates negatively with decreasing levels of Emilin-1 mRNA in the affected tissue, which confirmed the direct involvement of Emilin-1 in the regulation of degradation processes of ECM in the aortic wall." (PMID 29158612, 2017).